GDF15 (growth differentiation factor 15)
Diseases named in the same sentence as GDF15 in open-access papers (continued):
Sharing a sentence is not in itself a finding about the gene and the disease.
breast carcinoma (continued). "Also, increased serum GDF-15 levels were reported to be associated with metastatic prostate, colorectal, gastric, hepatocellular and breast carcinomas." (PMID 30646851, 2019). "Thus, future evaluation of the role of GFRAL and associated signaling pathways in EMT and invasion of GDF15-overexpressing breast cancer cells is warranted." (PMID 29212236, 2017). "In breast cancer, GDF15 overexpression drives the epithelial-mesenchymal transition (EMT) phenotype through the IGF-1R-FoxM1 signaling pathway." (PMID 40144214, 2025). "In breast cancer (BC), GDF15 expression correlates with high tumor grade, estrogen receptor (ER) negativity, and human epidermal growth factor receptor 2 (HER2) positivity." (PMID 40868185, 2025). "Generally, the GDF-15 level exhibited a skewed distribution in HER2-positive breast cancer patients." (PMID 38828460, 2024). "In the cancer cell literature, only two publications have reported contradictory effects of the WWTR1/TAZ paralog, YAP, which represses GDF15 expression in breast cancer and induces expression in hepatocellular carcinoma." (PMID 38201456, 2023). "This suggests that the p-Akt/FOXM1 axis mediates the relationship between increased GDF-15 expression and enhanced stemness and treatment resistance in breast cancer." (PMID 37569598, 2023). "Expect for the GDF15, the interaction between the S127A‐mutated YAP and TEAD also has an influence on breast cancer metastasis." (PMID 37576865, 2023). "Most of these genes were associated with cancers of metabolic systems (DUSP6, SGK1, BMP4, RASGRF1, GDF15) followed by breast cancer (CACNA2D3, ITGB7), cancers of the central nervous system (PRKCA), or leukemia (MECOM, JAK3)." (PMID 36624125, 2023). "It was demonstrated that stemness and indicators of treatment resistance were significantly positively correlated with GDF-15 expression in breast cancer patients." (PMID 37569598, 2023). "In the nucleus, YAP has been reported to inhibit the transcription of growth differentiation factor (GDF15) and then promotes breast cancer metastasis." (PMID 37576865, 2023). "One study addressed the antitumor effects of diltiazem, which reduced colony formation, cell migration, and EMT by increasing GDF-15 expression level through inhibiting its proteolytic degradation in different breast cancer cell lines in vitro." (PMID 36831338, 2023). "Several other studies have found GDF15 to contribute to the invasiveness and metastatic potential of breast cancer tumors through various signaling pathways, including p38 MAPK phosphorylation and EGFR transactivation." (PMID 36353620, 2022). "In conclusion, diltiazem attenuates colony formation, cell migration, and EMT by increasing GDF-15 expression level through inhibiting its proteolytic degradation in different breast cancer cell lines in vitro." (PMID 35963873, 2022). "Additional validation of GDF15 expression and secretion as a potential biomarker was performed in breast cancer patient-derived xenograft organoids (PDXO)." (PMID 35626166, 2022). "Breast cancer with high level of GDF15, especially in ErbB2 (HER2)-positive state, is sensitive to EGFR/ErbB2 inhibitor Lapatinib." (PMID 35853851, 2022). "In breast cancer, GDF15 has been found to enhance tumor proliferation and growth, potentially by increasing iron retention." (PMID 36353620, 2022). "The clinical tissue samples of breast cancer collected in the Zhao breast dataset of the Oncomine database showed that the mRNA expressions of GDF15 in both lobular breast carcinoma and invasive ductal breast carcinoma were higher than that in normal tissue." (PMID 36142823, 2022). "The TCGA database also revealed the relationship between the expression level of GDF15 and the clinicopathological characteristics of breast cancer patients." (PMID 36142823, 2022).
breast carcinoma (continued). "We further validated the relationship between GDF15 and the clinical profile of breast cancer patients by employing the Oncomine database and BRCA (breast invasive carcinoma) dataset of the TCGA database." (PMID 36142823, 2022). "It has also been reported that anti-cancer drugs, such as Phortress, enhances GDF-15 expression and tumor recession in breast cancers." (PMID 35963873, 2022). "Like M-CSF, both FGF-21 and GDF-15, as described in the current study, have been reported to be significantly elevated in the blood of female breast cancer patients, albeit based on very limited prior data." (PMID 35677046, 2022). "In conclusion, this study has brought about a novel prognostic indicator, GDF15, in predicting the survival of breast cancer patients post-radiotherapy with bioinformatic analysis and in vitro confirmation." (PMID 36142823, 2022). "Considering the EMT process endows the mesenchymal properties of cancer cells and reflects the ability of cancer cells to enter CSC status, we validated the function of GDF15 in maintaining the stemness of radioresistant breast cancer cells." (PMID 36142823, 2022). "Consistent with previous studies, we found that serum GDF-15 expression is decreased in breast cancer-bearing mice, and diltiazem-induced GDF-15 exhibits anti-tumor effects by decreasing EMT and metastatic nodules of breast cancer." (PMID 35963873, 2022). "Mechanically, GDF15 contributed to the radioresistance of breast cancer cells by enhancing the EMT process and stem-like traits." (PMID 36142823, 2022). "We will further explore the specific regulatory mechanism of GDF15 in radioresistant breast cancer stem cells in the future." (PMID 36142823, 2022). "Consistent with above results, after irradiation, the mRNA expression levels of GDF15 were also up-regulated in these breast cancer cell lines based on the RT-PCR and qRT-PCR assay, respectively." (PMID 36142823, 2022). "It was found that GDF15 was significantly up-regulated in the irradiated breast cancer cells and highly expressed in the stable radioresistant cell lines MDA-MB-231-RR and MCF-7-RR cells." (PMID 36142823, 2022). "On one hand, GDF15, a member of the TGF-β superfamily, has been linked with macrophages, adipocytes, and several carcinomas including breast cancer." (PMID 34071445, 2021). "More recently, we have demonstrated that visfatin not only directly influences breast cancer progression but also indirectly affects breast cancer through GDF-15 secretion in ADSCs, thus promoting breast cancer malignant behavior." (PMID 33256011, 2020). "Specifically, a recent study demonstrated the recruitment of myeloid cells to the tumor in a mouse mammary tumor model following treatment with doxorubicin and GDF15 can enhance the tumor-initiating and self-renewal potential of multiple myeloma cells." (PMID 33086658, 2020). "In our cohort of treatment‐naïve cancer patients, circulating GDF‐15 levels were comparable for most common tumour entities, except for slightly lower values in breast cancer." (PMID 31463975, 2019). "In conclusion, visfatin activated GDF15-AKT pathway mediated via ADSCs to facilitate breast cancer progression." (PMID 31861872, 2019). "GDF‐15 levels of the different tumour entities were comparable except for lower GDF‐15 levels in breast cancer patients." (PMID 31463975, 2019). "We found that visfatin and GDF15 had a positive correlation (r = 0.2513, p = 0.005) in the peripheral blood of the breast cancer patients." (PMID 31861872, 2019). "In the present study, we found that visfatin-treated ADSCs promoted malignant behaviors and tumor formation in breast cancer cells via a GDF15-induced AKT pathway." (PMID 31861872, 2019). "Emerging evidence has shown that GDF15 overexpression can facilitate tumor cells proliferation, e.g., ovarian cancer, breast cancer, and esophageal squamous cell carcinomas." (PMID 29773900, 2018).
breast carcinoma (continued). "We previously demonstrated that GDF15 induces PI3K and Erk1/2 phosphorylation in HER2-overexpressing breast cancer cells, in association with drug resistance." (PMID 29212236, 2017). "Further, based on the reduced invasiveness of HER2-positive and triple-negative breast cancers in response to GDF15 knockdown, future studies should evaluate GDF15 as a potential molecular target in breast cancer." (PMID 29212236, 2017). "BT474 and JIMT1 breast cancer cells express low levels of GDF15, whereas MDA-MB-231 (MDA231) breast cancer cells demonstrate high endogenous expression of GDF15." (PMID 29212236, 2017). "Using siRNA, GDF15 was transiently knocked down in HER2-positive BT474 empty vector pCMV control, BT474 GDF15-overexpressing stable clone, and triple-negative MDA-MB-231 breast cancer cells, which have endogenous overexpression of GDF15." (PMID 29212236, 2017). "GDF15 expression, as assessed by IHC, was correlated with baseline clinical characteristics in a cohort (N=592) of patients with breast cancer." (PMID 29212236, 2017). "GDF15-overexpressing breast cancer cells also demonstrated significantly increased invasion through basement membrane matrix." (PMID 29212236, 2017). "In the current study, we demonstrate that GDF15 is associated with high tumor grade, ER-negativity, and HER2 overexpression in patients with breast cancer." (PMID 29212236, 2017). "To determine if stable GDF15 overexpression also promotes EMT in breast cancer cells, we examined expression of mesenchymal and epithelial markers by western blotting." (PMID 29212236, 2017). "Our study supports the notion that GDF15 plays roles in CSCs not only in breast cancer but also in many other solid tumors." (PMID 28206960, 2017). "Exogenously added GDF15 induced tumor sphere formation in primary cancer cells derived from luminal A type breast cancer tissues, though endogenous expression levels of GDF15 were very low." (PMID 28206960, 2017). "In this study, we showed that GDF15 induces tumor sphere formation, an important property of CSCs, in breast cancer cells using patient-derived primary breast cancer cells." (PMID 28206960, 2017). "Our studies are the first to report activation of IGF-1R-FoxM1 as a mechanism of invasion in GDF15-overexpressing breast cancers, providing rationale for preclinical evaluation of treatments that co-target IGF-1R and FoxM1." (PMID 29212236, 2017). "Although increased expression of GDF15 is associated with advanced disease in patients with multiple types of malignancies, limited data are available regarding the expression levels of GDF15 in breast cancer." (PMID 29212236, 2017). "Expression levels of GDF15 are significantly higher in breast cancer tissues than in normal breast tissues." (PMID 28206960, 2017). "We showed that expression levels of GDF15 are heterogeneous among cancer cells, even in the same breast cancer tissues." (PMID 28206960, 2017). "We also showed that GDF15 induces its own expression in breast cancer cells through sustained activation of ERK1/2." (PMID 28206960, 2017). "Nevertheless, recently it was reported that overexpression of GDF15 (which is also observed in our experiment) induces apoptosis of breast cancer cells." (PMID 29362714, 2017). "Treatment with the broad-spectrum MMP inhibitor GM6001 significantly reduced invasiveness of stable GDF15-overexpressing clones, suggesting that MMPs contribute to the invasive phenotype of GDF15-overexpressing breast cancer cells." (PMID 29212236, 2017). "Several studies have also reported transient activation of ERK1/2 in HER2-overexpressing breast cancer cells by the transactivation of the ErbB2 (HER2) via GDF15-triggered TGFβ receptor-Src activation." (PMID 28206960, 2017). "GDF15 stable clones and breast cancer cells stimulated with recombinant human GDF15 (rhGDF15) demonstrate activation of insulin-like growth factor-1 receptor (IGF-1R), EMT, and invasion." (PMID 29212236, 2017).
breast carcinoma (continued). "Furthermore, GDF15 is able to facilitate metastasis of breast cancer cells to bone tissue via the activation of the receptor activator of nuclear factor-κB ligand (RANKL)." (PMID 40144214, 2025). "Similarly, GDF15 facilitates metastasis of breast cancer cells to bone tissue, which can be blocked by inhibition of the receptor activator of nuclear factor-κB ligand (RANKL)." (PMID 40144214, 2025). "Increased concentrations of GDF-15 were noted in cardiomyocytes during ischemia–reperfusion injury and myocardial infarction, in response to treatment with anthracyclines and trastuzumab in breast cancer patients." (PMID 38397436, 2024). "High levels of GDF15 may be a factor in trastuzumab resistance in HER2 overexpressing breast cancer cells through the activation of TGF-β receptor-Src-HER2 signalling crosstalk." (PMID 37569598, 2023). "Nevertheless, to date, it is still unclear whether GDF15 is relative to the radioresistance of breast cancer." (PMID 36142823, 2022). "Furthermore, overexpression of GDF-15 diminishes migration ability on both normal mammary gland epithelial cells and breast cancer cells." (PMID 35963873, 2022). "All referred evidence prompts that GDF15 is a promising radiotherapeutic target for breast cancer patients and targeting GDF15 may provide a new strategy for improving the radiotherapy efficiency of breast cancer patients." (PMID 36142823, 2022). "In one of these, encompassing various types of malignancy, including a small number of breast cancer patients (n=10), elevated serum levels of GDF-15 were detected in 6/10 patients, with the median value being significantly higher than that of a much larger group of control subjects (n=260)." (PMID 35677046, 2022). "Therefore, GDF15 mediated the radioresistance of breast cancer by maintaining the stemness of cells." (PMID 36142823, 2022). "Results confirmed our suspicions that interfering with GDF15 would enhance response to eribulin: significantly increased cell death was seen when breast cancer cells were treated with the combination of anti-GDF15 antibody plus eribulin as compared to the combination using a nonspecific control IgG." (PMID 35626166, 2022). "Accordingly, GDF15 promoted the EMT process of the radioresistant breast cancer cells." (PMID 36142823, 2022). "Conclusively, GDF15 may be applicable as a novel prognosis-related biomarker and a potential therapeutic target for breast cancer radiotherapy." (PMID 36142823, 2022). "Most importantly, our data suggest that the combination of eribulin plus a GDF15 neutralizing antibody might be beneficial in the treatment of breast cancer." (PMID 35626166, 2022). "Next, we want to know whether GDF15 plays an essential role in promoting the EMT process of radioresistant breast cancer cells." (PMID 36142823, 2022). "Collectively, these results suggest the possibility that combination treatment with eribulin plus GDF15 inhibitors could both enhance response and forestall the development of resistance in the breast cancer setting." (PMID 35626166, 2022). "The findings in the present study were also in concordance with previous studies that positively correlated elevated levels of GDF-15 with cardiac dysfunction in breast cancer patients, receiving chemotherapeutic agents, further supporting the predictive utility of this biomarker." (PMID 36034829, 2022). "Finally, we performed the GDF15 immunostaining on tissues from breast cancer PDXs treated in vivo with eribulin." (PMID 35626166, 2022). "Over-secretion of GDF15 induced by eribulin in our studies of breast cancer cell lines led us to investigate its potential as a pharmacodynamic (PD) response biomarker for eribulin, in addition to its potential utility as a specific biomarker for DTP cell generation." (PMID 35626166, 2022).
breast carcinoma (continued). "Moreover, knockdown of GDF15 sensitized the radioresistance cells to irradiation and significantly inhibited their EMT and stem-like traits, indicating that GDF15 promoted the radioresistance of breast cancer by enhancing the properties of EMT and stemness." (PMID 36142823, 2022). "Further investigation revealed that GDF15 could mediate the radioresistance of breast cancer cells by promoting the EMT properties and stem-like traits." (PMID 36142823, 2022). "Serum concentrations of GDF-15 were found to increase continuously during the 15-month follow-up of breast cancer patients treated with doxorubicin and trastuzumab, and increased GDF-15 levels were significantly associated with an increased risk of LVEF reduction." (PMID 34859069, 2021). "Lastly, GDF15 seems to be an important mediator of RSU1 functions both in breast cancer and in glioblastoma, but the molecular mechanism of its action, its interaction with RSU1 and possible modulators of that interaction are still unknown." (PMID 32517326, 2020). "GDF15 protein expression is markedly increased in various types of cancer biopsies including breast cancer, with our analysis of the Oncomine database also noting significantly higher GDF15 mRNA expression levels in breast cancer tissues than normal breast tissues." (PMID 31861872, 2019). "Further, we examined the serum levels of visfatin and GDF15 of breast cancer patients by ELISA." (PMID 31861872, 2019). "This study establishes a novel and important model for future stromal-tumor analysis in breast cancer, and highlights previously unknown therapeutic targets in the GDF15-pAKT pathway." (PMID 31861872, 2019). "Using the Cancer Cell Line Encyclopedia (CCLE) database, we found a correlation between centrosome amplification and the expression of the secreted pro-invasive factors, excluding GDF-15, in a panel of breast cancer cell lines, which we previously characterized for centrosome amplification." (PMID 30458137, 2018). "Here, we show that the growth differentiation factor 15 (GDF15), a member of the TGFβ family, may maintain cancer stem-like cells in breast cancer tissues by inducing its own expression in an autocrine/paracrine manner." (PMID 28206960, 2017). "In addition, we found heterogeneous expression levels of GDF15 among cancer cells and in human breast cancer tissues using immunohistochemistry." (PMID 28206960, 2017). "Cells with high levels of GDF15 may maintain GDF15 production by the autocrine/paracrine circuit and act as cancer stem-like cells in breast cancer." (PMID 28206960, 2017). "Knockdown of GDF15 significantly inhibited breast cancer invasion through basement membrane matrix." (PMID 29212236, 2017). "Knockdown of FoxM1 rescued EMT and invasiveness of GDF15-overexpressing breast cancer cells." (PMID 29212236, 2017). "Finally, we showed that expression levels of GDF15 are heterogeneous among cancer cells from human breast cancer tissue samples." (PMID 28206960, 2017). "We next examined the expression of GDF15 in various subtypes of breast cancer tissues." (PMID 28206960, 2017). "We chose to use the MCF7 breast cancer cells because they show a good response to GDF15." (PMID 28206960, 2017). "On the other hand, it is still largely unknown whether GDF15 has any roles in CSCs from a vast majority of tumors, including breast cancer." (PMID 28206960, 2017). "Thus, according to these studies, which included a relatively small number of patient samples, GDF15 expression was elevated in 50% to 60% of serum or tumor tissue specimens from patients with breast cancer." (PMID 29212236, 2017). "To further elucidate the molecular mechanism through which GDF15 enhances breast cancer cell invasion, we measured expression levels of matrix metalloproteinases (MMP) MMP2 and MMP9, which are transcriptional targets of FoxM1 and mediators of cancer cell invasion." (PMID 29212236, 2017).